snoZ196 (Small nucleolar RNA Z196/R39/R59 family )
Gene: Small nucleolar RNA gene on chromosome 2 (206,161,841 to 206,161,929, forward strand). Ensembl gene ENSG00000281780.
Gene Ontology:
Biological process: RNA processing
Cellular component: nucleolus
Homologues: Orthologues: chimpanzee snoZ196 (100% identical), guinea pig snoZ196 (39% identical), mouse Gm26457 (38% identical).